VIM (vimentin)
Diseases named in the same sentence as VIM in open-access papers (continued):
Sharing a sentence is not in itself a finding about the gene and the disease.
breast carcinoma (continued). "In addition, combination ROC indicated that these genes (ZEB2‐AS1, ZEB2, vimentin, and E‐cadherin) could have the potential to diagnostic of breast cancer metastasis." (PMID 37088469, 2023). "Furthermore, vimentin expression has been associated with poor outcome in breast cancer." (PMID 23295955, 2013). "In breast carcinoma cells, Twist causes transcriptional repression of E-cadherin, α, β and γ-catenins, and stimulates the expression of mesenchymal cell markers like fibronectin, vimentin, α-smooth muscle actin and N-cadherin as well as the angiogenic factor VEGF." (PMID 19851501, 2009). "After ZEB1 overexpression, the EMT pathway of BT549 and MB231 breast cancer cells was up-regulated, as shown by the increase in N-cadherin and Vimentin expression." (PMID 41158758, 2026). "In contrast, HS578T-Hyg breast cancer exhibited a classical mesenchymal phenotype as evidenced by the absence of E-Cadherin and Snail expression and the presence of Vimentin, which is also consistent with prior research." (PMID 40471394, 2025). "Vimentin belongs to the intermediate filament family of proteins, and it is highly expressed in many epithelial tumors, such as breast cancer, prostate cancer, melanoma, and lung cancer." (PMID 40332096, 2025). "Vimentin, proposed to maintain mechanical integrity during invasion, correlated with cell stiffening in lung and breast cancer cells." (PMID 39759848, 2025). "Overexpression of Vimentin has been found in many epithelial tumors, including lung cancer, prostate cancer, gastrointestinal tumors, breast cancer, and central nervous system tumors." (PMID 40457691, 2025). "A marked decrease in E-cadherin and increase in N-cadherin and Vimentin was observed in alpelisib-resistant cell lines, Therefore, we have successfully established the alpelisib-resistant breast cancer cell line model." (PMID 40303291, 2025). "ThPOK-kd led to an increase in the expression of EMT factors (VIM, SNAI2, ZEB1, ZEB2), basal markers and WNT/β-catenin target genes implicated in breast cancer cell proliferation." (PMID 41231242, 2025). "We also investigated the effect of mutant vimentin downregulation on breast cancer stem cell markers CD56/NCAM1 and CD201/PROCR in C328S-VIM-expressing cells upon shRNA treatment." (PMID 40690373, 2025). "RNA‐seq and proteomic profiling revealed significant APA in PICK1 following VIM KO, suggesting a novel mechanism by which VIM regulates breast cancer progression." (PMID 39781570, 2025). "In particular, the expression levels of SNAI2/Slug and vimentin (VIM), which are crucial regulators of mesenchymal transition in breast cancer, were evaluated after treatment with each inhibitor as well as their combination." (PMID 40943584, 2025). "The epithelial marker E-cadherin is only expressed in the ER+ breast cancer cells, while the mesenchymal marker vimentin is only expressed in the ER− breast cancer cells." (PMID 40149544, 2025). "Several studies have shown that PAL reduces expression of mesenchymal markers such as Vimentin and Snail while restoring epithelial markers like E-cadherin, thereby inhibiting migration and invasion of breast cancer cells." (PMID 40569965, 2025). "Statins, such as simvastatin and mevastatin, promote the bundling of vimentin and exhibit selective cytotoxicity toward mesenchymal breast cancer cells expressing vimentin." (PMID 39930669, 2025). "Breast cancer continues to be a major health issue for women worldwide, with vimentin (VIM) identified as a crucial factor in its progression due to its role in cell migration and the epithelial‐to‐mesenchymal transition (EMT)." (PMID 39781570, 2025). "When small interfering RNA was used to interfere with vimentin expression, the migration ability of breast cancer cells MDA‐MB‐231 was weakened, and the adhesion of MDA‐MB‐231 cells was also reduced." (PMID 39781570, 2025).
breast carcinoma (continued). "For this reason, they sought lncRNAs microRNA as an entry point to interfere with the expression of vimentin and thus inhibit the metastasis of breast cancer." (PMID 39781570, 2025). "For example, Luminal and HER2(+) breast cancers exhibited higher numbers of CD34(+)/CD10(+)/c-Kit(+)/vimentin(+) telocytes than triple-negative breast cancers." (PMID 40724542, 2025). "In MCF7 breast cancer cells, the increase in vimentin levels improved cell stiffness and motility, resulting in the induction of EMT following the downregulation of E-cadherin." (PMID 40332096, 2025). "Inhibition of CDH11 has also been reported to inhibit tumor growth by suppressing the expression of β‐catenin and vimentin in mouse models of breast cancer." (PMID 41263259, 2025). "Using the antimicrobial peptide merecidin to increase the expression of miR-770-5p can negatively regulate vimentin, thereby delaying the metastasis and proliferation of breast cancer cells." (PMID 40723842, 2025). "To further study the functions of VIM in protein level, we performed LC–MS/MS analysis to profile the protein levels of both WT and VIM KO breast cancer cells (4T1)." (PMID 39781570, 2025). "In another study, c-Kit(+), CD34(+), and vimentin(+) telocytes promoted the growth of EMT6 breast cancer cells and inhibited apoptosis in vitro." (PMID 40724542, 2025). "In breast cancer cells, overexpression of Vimentin enhances cell hardness, motility, and directional migration ability, reorients microtubule polarity, and increases the EMT phenotype." (PMID 41153737, 2025). "Preclinical and early-phase clinical trials are essential to evaluate the safety, efficacy, and optimal integration of BMPs, SDF-1, and vimentin in the clinical setting of breast cancer." (PMID 39859358, 2025). "Our study revealed that VIM‐KO significantly alters both the transcriptome and proteome of breast cancer cells, specifically increasing the expression of short 3′‐UTRs." (PMID 39781570, 2025). "The bioinformatics analysis provided valuable insights into the possible prognostic and therapeutic significance of BMP-2, BMP-4, SDF-1, and vimentin in breast cancer." (PMID 39859358, 2025). "To investigate the roles of VIM in transcription regulation, we performed RNA‐seq experiments on both VIM‐KO and WT breast cancer cell line—4T1." (PMID 39781570, 2025). "The 67NR cell line originates from the same primary breast cancer source as 4T1 and expresses N-cadherin and vimentin, but it lacks E-cadherin expression." (PMID 40643464, 2025). "In VIM KO group, the VIM protein level was reduced to 6.5% compared to WT breast cancer cells, confirming the efficient of VIM knockout in VIM KO cells." (PMID 39781570, 2025). "As vimentin is a marker of highly metastatic potential in breast cancer, the disruption of the vimentin network signalizes the development less malignant phenotype under microgravity conditions." (PMID 40124331, 2025). "To select suitable cell lines, we first assessed the expression of the epithelial molecule EpCAM and the mesenchymal protein vimentin across a panel of breast cancer cell lines by Western blot analysis." (PMID 41509313, 2025). "TWIST can downregulate E-cadherin and activate N-cadherin and vimentin, and it is vital for tumor cell dissemination and metastasis in breast cancer." (PMID 40830747, 2025). "Loss of epithelial markers, such as E‐cadherin, and gain of mesenchymal markers, such as vimentin and N‐cadherin, are associated with poor prognosis and reduced survival in HNSCC, NSCLC, and breast cancer." (PMID 40895189, 2025). "CircScrib570 inhibits pre-mRNA splicing and translation, upregulates E-cadherin, and downregulates N-cadherin and vimentin, thereby promoting breast cancer proliferation and invasion." (PMID 40804731, 2025). "Specifically, higher expression of vimentin, a mesenchymal marker, was observed in triple-negative human breast cancer and feline mammary tumors, indicating a more aggressive phenotype." (PMID 40286049, 2025).
breast carcinoma (continued). "Vimentin expression correlates with tumor size and higher histological grade in breast cancers of young women." (PMID 38935814, 2024). "In the present study while whole blood exposure to hormone-therapy treated breast cancer cells decreased ESR1 expression substantively, corresponding changes in EMT-associated genes indicated higher levels of CDH1 and vimentin in T47D cells than MCF7 cells." (PMID 38233507, 2024). "In another finding, miRNA-30c regulates invasion of breast cancer by targeting the cytoskeleton network genes encoding Twinfilin 1 (TWF1) and Vimentin (VIM), both of which regulate EMT." (PMID 38540304, 2024). "Downregulation of HIF-1α by miR-622, which deactivates genes within the EMT pathway, culminates in decreased levels of Snail, Slug, and vimentin proteins through miR-30a, consequently attenuating the invasion and migration capacities of breast cancer cells." (PMID 38339408, 2024). "Another research reports the impact of FERM domain-containing protein 3 (FRMD3) on vimentin degradation, resulting in anti-proliferative and anti-metastatic roles in breast cancer." (PMID 38191501, 2024). "Increased vimentin expression is observed in several types of cancer, such as breast cancer, melanoma and lung cancer." (PMID 38383479, 2024). "In our study, propranolol downregulated vimentin and upregulated E-cadherin expression in breast cancer cells." (PMID 38294713, 2024). "In breast carcinoma, a loss of miR200 induces EMT via decreased E-cadherin and increased vimentin expression." (PMID 38398019, 2024). "An upregulation of E-Cadherin and a downregulation of vimentin in relation to the epithelial phenotype were also reported in response to mifepristone in breast cancer cells." (PMID 39201464, 2024). "In studies where breast cancer cells were transfected with a vimentin overexpression vector, an increase in motility was observed, while silencing vimentin decreased it." (PMID 38542313, 2024). "Through the use of an immunofluorescence test, CuB was found to reduce the intensity of F-actin/vimentin/FAK/vinculin in breast cancer cells." (PMID 38563878, 2024). "In this study, we found that vimentin intermediate filaments (VIFs) frequently accumulated at the concave of dysmorphic nucleus in breast cancer MDA-MB-231 cells." (PMID 39542246, 2024). "Western blotting analysis confirmed that siFXR reversed TGF-β1-induced metastasis of breast cancer cells by downregulating mesenchymal markers (N-cadherin and vimentin) and upregulating the epithelial marker E-Cadherin." (PMID 39543094, 2024). "Regarding the underlying mechanisms, it caused a decrease in the expression of F-actin, vimentin, FAK, and vinculin, leading to changes in the distribution and rearrangement of cytoskeletal proteins in breast cancer cells." (PMID 38563878, 2024). "Accordingly, silencing vimentin expression decreased pulmonary metastases in a pre-diabetic mouse model of mammary tumor progression." (PMID 38999849, 2024). "Immunoblotting of mammary tumour chunks showed dramatic upregulation of HIF1α that was concomitant with increased VIM, SNAI1, TWIST and decreased E-CAD expression in GPx2 KD relative to control tumours." (PMID 38238426, 2024). "Forced coexpression of luminal keratins 8 and 18 with vimentin in human breast cancer cells in vitro increases motility, invasiveness, and proliferation." (PMID 37963845, 2023). "The increased expression of Vimentin in the epithelial breast cancer cells, due to CRERB1 and over expression of ERβ4 alludes to the possibility of cells undergoing EMT, and increased transcripts of ALDH1 indicate increase in BCSC subpopulation." (PMID 36982940, 2023). "This image proves that the RFP tagged Vimentin gene which is upregulated in the EMT changes of breast cancer cells is correctly in frame inserted by the CRISPR-CAS9 technique in the genome of these TNBC cells and inducing EMT." (PMID 37538932, 2023).
breast carcinoma (continued). "In terms of the regulation of specific mesenchymal markers, ER ATPase inhibitor thapsigargin is an inducer of vimentin in breast cancer cells, which involves store-operated Ca2+ entry." (PMID 36890838, 2023). "To validate the data, in an independent patient cohort, we compared the expression changes of ZEB2‐AS1, ZEB2, E‐cadherin, and vimentin in human BC samples from different stages of breast cancer." (PMID 37088469, 2023). "Overexpression of the ER secretion factor ER protein 29 in breast cancer cells results in enhanced MET phenotypes, including stress fiber loss, E-cadherin upregulation, and vimentin downregulation." (PMID 36890838, 2023). "Collectively, these results indicate that silencing Notch4 in TNBC cells suppresses breast cancer migration in vitro via the location of Vimentin expression." (PMID 37149651, 2023). "For example, in colorectal cancer, lung cancer, breast cancer, and glioblastoma, increased expression of vimentin enhanced cell migration and invasion." (PMID 36912679, 2023). "A total of 321 CD45-/CK+ rare cells from six breast cancer patients and one additional prostate cancer patient were scored for vimentin expression and sequenced to determine genomic clonality." (PMID 37568766, 2023). "As we anticipated, the immunofluorescence results revealed that E-cadherin upregulation as well as Snail/Vimentin downregulation occurred in breast cancer cells following PNKY silencing." (PMID 37104007, 2023). "An ALK5 inhibitor, vactosertib, can down-regulate the EMT markers (Vimentin, Snail, Slug, Twist) thus being considered as an option to prevent metastasis, when radiotherapy is applied to breast cancer patients." (PMID 37333824, 2023). "The E3 ubiquitin has been reported to promote Vimentin ubiquitination and degradation in breast cancer cells." (PMID 37740460, 2023). "In the case of breast cancer, tumorigenic events, such as tumor cell migration and invasion of cancer cells, are highly correlated to the overexpression of vimentin." (PMID 37475865, 2023). "On the contrary, over-expression of Vimentin in breast cancer cells induces EMT and increases cell stiffness." (PMID 37864030, 2023). "SALL4 induced epithelial-mesenchymal transition and promoted tumor progression in breast cancer by directly binding to the vimentin promoter." (PMID 37525212, 2023). "Vimentin contributes to the aggressive phenotype in invasive breast cancer and is considered a canonical marker of EMT, which plays a role in tumor invasion and progression." (PMID 36674719, 2023). "This study aimed to investigate ZEB2‐AS1, ZEB2, E‐cadherin, and vimentin expression in human breast cancer patients and expression changes in these genes at different stages of BC." (PMID 37088469, 2023). "It has been shown that W. somnifera root extracts can inhibit vimentin, a protein normally found in regions of metastasis, thus suggesting its counteracting effects on tumour formation in breast cancer." (PMID 36865913, 2023). "The necropsy of a mouse showing remission in palpable tumors showed a 2 mm diameter carcinoma, like a bulb of tissue, that was stained for pan-cytokeratin and vimentin via immunohistochemistry, and verified as breast carcinoma." (PMID 37515069, 2023). "For example, it was found that knockdown of Src or treatment with Src kinase inhibitors downregulated the expression of Slug and vimentin but increased E-cadherin expression in breast cancer cells and head and neck squamous cell carcinoma (HNSCC) cells." (PMID 37110648, 2023). "The results of pathway analysis in ductal type recurrence breast cancer in this study showed a significant influence between vimentin expression and MMP1 expression (p=0.000) and had a strong correlation between the two (β=0.611)." (PMID 38046195, 2023).
breast carcinoma (continued). "The EMT profile of each breast cancer cell line under study was evaluated by measuring the protein levels of the epithelial marker E-cadherin and of the mesenchymal markers fibronectin, vimentin and αSMA by Western Blot analysis." (PMID 36454513, 2023). "Of note, increased expression of vimentin is found in stiffer breast cancer cells and facilitates EMT and cancer cell invasiveness." (PMID 37864030, 2023). "This study aimed to analyze CTCs and cCAFs simultaneously in the peripheral blood of 210 breast cancer patients using DAPI/pan-keratin (K)/vimentin (V)/alpha-SMA/CD29/CD45/CD31 immunofluorescent staining and novel technology—imaging flow cytometry (imFC)." (PMID 37627197, 2023). "Studies related to Vimentin in breast cancer cells have considered it a new target for therapeutics and have shown it to be associated with the recurrence of triple-negative breast cancer (TNBC)." (PMID 38201482, 2023). "SUMO1/2 and PIAS1 have been reported to promote SUMOylation of vimentin, which plays an important role in enhancing breast cancer metastasis." (PMID 37833712, 2023). "Vimentin is highly expressed in epithelial tumors (prostate cancer, gastric cancer, malignant melanoma, and lung cancer); however, in breast cancer, aberrant expression of vimentin is restricted to TNBC." (PMID 36769215, 2023). "Studies have shown that high vimentin expression with loss of E-cadherin is associated with the EMT of various cancers, including breast cancer." (PMID 37370134, 2023). "Previously, we demonstrated that F3 had anti-metastatic activity in breast cancer by reducing the expression of N-cadherin, vimentin, MMP-9, MUC1, Twist, and VEGF, while increasing the expression of E-cadherin." (PMID 37259304, 2023). "In CMTs, vimentin expression is low (approximately 15%), con-firming the low aggressiveness of mammary tumors in dogs, which is in concordance with the findings of other authors." (PMID 36899736, 2023). "Consistent with the in vitro results, miR-29a induced the mRNA and protein levels of the EMT markers vimentin, fibronectin and snail in the mammary tumors." (PMID 37081505, 2023). "Conversely, in FMTs, the expression of vimentin, although heterogeneous, was quite high (approximately 70%), suggesting the high aggressiveness of mammary tumors in this species, as well as their similarities with TNBCs." (PMID 36899736, 2023). "Our results indicate: (i) exosomes promote tumor cell migration; (ii) Mortalin and Vimentin are involved in tumor migration; and (iii) SMRwt peptide inhibits breast cancer cells’ migration and invasion." (PMID 35915218, 2022). "This vimentin-integrin interaction supports breast cancer cell migration and in vivo lung metastasis formation." (PMID 35990612, 2022). "Treatment with SMRwt of MDA-MB-231 and MCF-7 breast cancer cells resulted in lowered exosome protein expression of Mortalin to 31.02% and 22.88% and Vimentin to 41.14% and 53.31%." (PMID 35915218, 2022). "In MDA-MB-231 and SKBR-3 breast cancer cell lines, CuB (30 nM) altered the cytoskeletal organization with reduced vimentin along with increased F-actin aggregates in the perinuclear area." (PMID 36355554, 2022). "Solid Tumors: In an in vivo xenograft model using breast cancer cells, phloretin (Ph, 100–150 mg/kg), a polyphenol from apple, reduced tumor weight as well as N-cadherin and vimentin expression." (PMID 36355554, 2022). "For instance, through direct interaction with the 3’ UTR of vimentin mRNA and its subsequent downregulation, miR-30a supresses the invasive phenotypes of breast cancer cell lines while miR-17-5p inhibits the metastasis of colorectal cancer in liver tissues." (PMID 35359446, 2022). "Immunohistological analyses of the constructs revealed that the origin of the tissue was derived from breast cancer cells, which stained positive for pan-cytokeratin but also for vimentin." (PMID 35877331, 2022).